MLANA (melan-A)
Diseases named in the same sentence as MLANA in open-access papers (continued):
Sharing a sentence is not in itself a finding about the gene and the disease.
melanoma (continued). "In addition, qRT-PCR analyses revealed a comparable Grm1 mRNA expression level of cultivated Tg(Grm1) cell lines to murine cerebellum (positive control, set as 1), whereas the murine B16 melanoma and melanocytic Melan-A cell line (negative control) displayed extremely low Grm1 expression." (PMID 31591386, 2019). "These tumors were identified to contain a small subpopulation of cells with high expression levels of Melan A. However, the immunohistochemical identification of focal positivity for Melan A in otherwise (clinically) clear-cut breast carcinoma must not be interpreted as melanoma metastases." (PMID 23599796, 2013). "Metastatic melanoma is characteristically negative for cytokeratins and squamous markers but shows strong positivity for melanocytic antigens, including S100, SOX10, Melan-A, HMB-45, and MITF." (PMID 41234990, 2025). "The melanoma case with absent PRAME expression exhibited diffuse S-100 and Melan-A expression, with HMB-45 expression present in both superficial and deep components." (PMID 41153267, 2025). "While peptide- and antigen-focused vaccines like GVAX (GM-CSF-secreting vaccine) or Melan-A/MART-1 and gp100 Peptides are being explored, dendritic cell vaccines have not shown sufficient promise to remain a focus in melanoma immunotherapy." (PMID 39857682, 2025). "We report a single benign acral pigmentary lesion characterized by conspicuous keratinocyte macromelanosomes, normal basal melanocyte density and architecture (Melan-A/SOX10), Fontana-Masson positivity, Perls negativity, and no histologic features of melanoma." (PMID 41426734, 2025). "B16-F10 cells are mouse melanoma cells that readily engraft and form aggressive tumors in immunocompetent C57BL/6 mice, while Melan-A cells are immortalized but non-tumorigenic melanocytes derived from the same C57BL/6 background 24,25." (PMID 38302465, 2024). "There was no reactivity of the WT– and A97L–T cells against the A2+/NY– melanoma tumor cell line NA8, nor did Melan-A–TCR–T cells show any reactivity above background levels against NA8, A375, and Saos-2." (PMID 38828721, 2024). "Mucosal melanoma histopathological findings are most commonly positive for S-100 and vimentin, occasionally positive for human melanoma black-45 (HMB-45) and Melan-A, and usually negative for cytokeratin and epithelial membrane antigen." (PMID 39006602, 2024). "positive HMB45 and Melan-A in the plantar confirmed the diagnosis with malignant melanoma, while the ankle tumor is negative for HMB45 and Melan-A." (PMID 37352079, 2023). "All 13 cases that were tested for melanoma markers were reported as negative (HMB-45, Melan-A, or melanoma cocktail)." (PMID 35200608, 2022). "Both mOS-REp were positive for the melanoma markers S100, HMB-45, Melan-A and MITF, while OS-REp was unambiguously negative." (PMID 36175453, 2022). "However, some melanoma patients have metastatic disease without evident primary lesion and in this case, the disease development is associated with immunoediting mechanisms together with loss of immunohistochemical melanocytic markers like S100 protein, HMB-45, Melan-A, SOX10 and MITF." (PMID 35495634, 2022). "In particular, double IHC assays combining these markers with others for melanoma, although not tumor-exclusive (S-100, MART-1, Melan A and MITF), were performed to better identify foci of lymphatic invasion in melanoma." (PMID 34207514, 2021). "Melanoma, on the other hand, is typically positive for c-kit, CD68, S-100, HMB-45, Melan-A, throsinase, and vimentin, and negative for smooth muscle actin, desmin, chromogranin, and epithelial membrane antigen." (PMID 33478436, 2021). "From the conventional pan-melanoma cocktail members, a significantly higher rate of positivity was highlighted by HMB-45 (92.38%) and tyrosinase (91.42%), but not by melan-A (92.38%) compared to their benign counterpart." (PMID 33801642, 2021).
melanoma (continued). "Regarding the IHC markers, the conventional pan-melanoma cocktail, the conventional-adapted pan-melanoma cocktail and, particularly, HMB-45 and tyrosinase, but not melan-A, proved to have an independent prognostic value." (PMID 33801642, 2021). "Cluster differentiation 68 (CD68) and CD163 were positive and S100, CD1a, langerin, human melanoma black 45 (HMB-45) and Melan-A were negative in immunohistochemical staining." (PMID 32532290, 2020). "We did not detect transcripts for melanoma antigens, gp100, Dopachrome tautomerase (DCT), Tyrosinase (Tyr), Melan-A and detected low levels of expression of Melanocyte Inducing Transcription Factor (MITF) in SB-3123p cells." (PMID 32231230, 2020). "Based on the surgical specimens, although there were no melanocytes, we made a diagnosis of a malignant melanoma immunohistochemically; the tumor cells were positive for S-100 protein and HMB45 focally and partially for Melan-A." (PMID 30635729, 2019). "S-100 therefore seems to be the most sensitive marker for melanoma, while HMB-45 and Melan-A demonstrate relatively good specificity but not as good sensitivity as S-100." (PMID 30635729, 2019). "The tumor cells were positive for AE1/AE3, S-100 protein, melan A, HMB-45, synaptophysin, calcitonin, chromogranin A, melanoma, and thyroid transcription factor-1 (TTF-1) and negative for thyroglobulin." (PMID 30424779, 2018). "Immunohistochemistry was positive for melanocytic features of Melan A (MART1; melanoma antigen recognized by T cells-1), human melanoma black-45, vimentin, and S-100 protein and negative for cytokeratin AE1/AE3 and glia fibrillary acidic protein." (PMID 29941032, 2018). "In human melanoma samples, expression of MYSM1 was increased compared with normal skin melanocytes and nevi and co-localized with melanocyte markers such as Melan-A and c-KIT." (PMID 28978033, 2017). "Although Gomisin N significantly inhibited melanogenesis in Melan-A and B16 cells as well as in zebrafish embryos, we did not observe its effect on human MNT-1 melanoma cells." (PMID 28241436, 2017). "In Paget disease, the positive epithelial markers are CK7, EMA, CEA, and mucin, whereas Melan A, HMB45, and S100 are negative in Paget disease but positive in cases of melanoma." (PMID 26060586, 2015). "Expression of Melan-A coincided with the GFP in melanoma cells, while white blood cells showed neither GFP nor Melan-A, collectively indicating high specificity for the telomerase-based CTC assay." (PMID 25807549, 2015). "In additional, there were subsets of melanoma cases without staining for S100 protein, HMB-45, and MART-1/Melan-A." (PMID 23028750, 2012). "The MART-1/Melan-A-negative melanoma cell line Mel A375 and the MART-1/Melan-A-positive melanoma cell line Mel-93.04A12 were used as controls." (PMID 20920165, 2010). "Melanoma commonly demonstrates positivity for S100, HMB45, Melan-A, and negative for EMA." (PMID 40909953, 2025). "However, the absence of melanoma markers, including HMB45 and Melan-A, and the negative molecular profile for any melanoma-associated genetic alterations, including BRAF, NRAS, and NF1 gene alterations, argued against such an entity." (PMID 40978976, 2025). "All other markers tested were negative (pan-melanoma, HMB45, Melan A, keratin AE1/AE3, desmin, alpha smooth muscle actin, h-caldesmon, CD34, p16, CD117, DOG1, myogenin, CD10, estrogen receptor (ER), progesterone receptor (PR), PAX8, WT1, synaptophysin, chromogranin A, CD99 and PRAME))." (PMID 39196362, 2024). "The lack of S100, Melan-A, and HMB45 immunoreactivity excluded malignant melanoma." (PMID 37735286, 2023). "Negative staining for immunoperoxidase techniques such as S100, HMB-45, melan-A (MART-1), and NKI/C3 can be of great help in distinguishing sebaceous carcinomas from melanomas, with the exception of melanomas with little or no pigmentation or spindle cell growth pattern." (PMID 37238164, 2023).
melanoma (continued). "In both proliferative phenotype melanoma cell lines, knockdown of SMAD4, TAZ, and β-catenin, but not of YAP, significantly counteracted the TGFβ-induced down-regulation of the expression of the melanocyte markers MITF and MLANA." (PMID 34819356, 2022). "The 15 negative conventional pan-melanoma-cocktail cases were represented by 9 cases with SOX11/SOX10/MITF triple positivity, 4 cases expressing only SOX10 positivity, and 2 cases that expressed HMB-45 and melan-A." (PMID 33801642, 2021). "Although HMB45 and Melan A are negative in neurothekeoma, it is known that spindle cell type melanoma can be negative for HMB45 and also Melan A. Hence, immunohistochemistry may not help in arriving at a definitive diagnosis in these S100 positive tumours." (PMID 27672465, 2016). "Due to the high stringency of our search, ESTs for genes traditionally known as melanocyte/melanoma-specific genes, such as TYR (Hs.503555), DCT (Hs.301865), MLANA (Hs.154069), and SILV (Hs.95972), were not selected because they also match entries of other tissue datasets." (PMID 20975957, 2010). "However, histological findings showed an undifferentiated neoplasm and none of the immunohistochemical stains for melanoma, including S100, HMB-45, Melan A, tyrosinase, CK, CD-34, c-Kit and LCA were able to clarify its origin." (PMID 18445301, 2008). "Furthermore, undifferentiated and dedifferentiated melanomas often occur in older individuals, which may explain the significant negative correlation observed between HMB45 and Melan-A and patient age." (PMID 41155720, 2025). "We found DLC1 and a melanoma marker MELAN A exhibited high correlation of their expression (χ2 = 4.546, p < 0.033) in a large percentage of melanomas (29/45; 64.4%) compared with other specimens expressing either DLC1 (5/45; 11.1%) or MELAN A alone (6/45; 13.3%) and neither of them (5/45; 11.1%)." (PMID 32214200, 2020). "Consistent with published reports in human melanoma, Dicer expression in B16F0 (non-metastatic) and B16F10 (metastatic) was significantly higher compared to the 4T1 and CT26 cell lines and was also significantly elevated relative to normal murine melanocytes (Melan A)." (PMID 27356752, 2016). "Malignant melanoma, GIST, MPNST, sarcomatoid renal cell carcinoma, and malignant fibrous histiocytoma will be positive for vHMB-45, c-kit, S-100, RCC marker, and CD68, respectively, and will be negative for desmin, synaptophysin, inhibin, Melan-A, and calretinin." (PMID 25685588, 2015). "However, malignant melanomas express S-100, HMB45, and Melan A which is lacking in MRTs." (PMID 25243090, 2014). "Subsequently, we extended the inhibitory receptor analysis to patients after vaccination with Melan-A peptide, with or without the addition of CpG-ODN 7909 to the vaccine formulation, and compared the data to the other two conditions, i.e. healthy donors and melanoma patients before vaccination." (PMID 22347406, 2012).
PEComas (30 papers, 2007 to 2025). "The immunoreactivity of HMB45, SMA, Melan-A, Vimentin, and Desmin in PEComas has been extensively discussed, along with the progression of TFE3 staining positivity in PEComas." (PMID 38689335, 2024). "Hepatic PEComas are quite rare and diagnosis involves positivity of Melan-A and HMB45 on immunohistochemistry." (PMID 24489554, 2013). "Additionally, immunohistochemical markers such as CD10+, HMB45-, melan-A-, and melanocyte-inducing transcription factor help to differentiate them from PEComas." (PMID 39540153, 2024). "Over half of the PEComas (57%) were immunoreactive to Melan-A." (PMID 38664269, 2024). "These tumors strongly express diffuse positiveness for HMB-45 and TFE-3, whereas it is weakly positive or negative for SMA and negative for melan A. TFE 3-associated PEComas can be associated with prior history of chemotherapy." (PMID 35232443, 2022). "Immunohistochemically, PEComas exhibit positivity for melanocytic markers such as HMB-45 and melan-A." (PMID 40002892, 2025). "Immunohistochemically, PEComas are positive for both smooth muscle markers (e.g., SMA, h-caldesmon, desmin) and melanocytic markers (e.g., HMB45, melan-A, tyrosinase, MITF)." (PMID 40002892, 2025). "PEComas are distinguished by the expression of smooth muscle markers (e.g., SMA, h-caldesmon, desmin) and melanocytic markers (e.g., HMB-45, melan-A, MITF)." (PMID 40002892, 2025). "PEComas are also characterized by specific transcriptomic features of the overexpressed DAPL1, MLANA, SULT1C2, GPR143 and CHI3L1 genes, as well as epigenetic features of lysosomal and melanocyte proteins as biomarkers." (PMID 40989692, 2025). "PEComas are characterized by the immunoexpression, among others, of both melanocytic markers (HMB-45, Melan-A, MiTF, and PNL2) and myoid markers (desmin, smooth muscle actin, muscle-specific actin, myosin, and calponin)." (PMID 40647483, 2025). "Gynecologic perivascular epithelioid cell tumors (PEComas) are rare mesenchymal neoplasms characterized by the co-expression of melanocytic markers (HMB-45 and Melan-A) and smooth muscle markers (SMA, desmin, and caldesmon)." (PMID 40647483, 2025). "PEComas are immunoreactive for both smooth muscle (desmin, SMA, muscle-specific-actin, muscle myosin, and calponin) and melanocytic (HMB-45, Melan-A/MART-1, tyrosinase, and MITF) markers." (PMID 39759135, 2024). "In a study aiming to distinguish PEComas from uterine smooth muscle tumors, twenty-one uterine PEComas and 45 SMTs were analyzed for PNL2; HMB45, Melan-A, Cathepsin-K, Desmin, and h-Caldesmon." (PMID 38664269, 2024). "Perivascular epitheloid cell tumor (PEComas) are characterized by expression of both muscles, most often smooth muscle actin (in ~80% of cases) and melanocytic markers (mainly HMB-45 and Melan A)." (PMID 35232443, 2022). "Since PEComas are almost always immunoreactive for smooth muscle (actin, desmin, caldesmon) markers, as well as melanocytic (HMB-45, melan-A, MiTF) markers, this characteristic immunohistochemical profile provides accurate diagnosis." (PMID 34442003, 2021). "Since PEComas are nearly always immunoreactive for both melanocytic (HMB-45, melan-A, MiTF) and smooth muscle (actin, desmin, caldesmon) markers, characteristic histologic and immunohistochemical findings provide the most accurate means of diagnosis." (PMID 28270196, 2017). "Almost all the PEComas were identified to be strongly positive for melanocytic markers (HMB-45 and/or melan-A) and smooth muscle markers (SMA and/or desmin)." (PMID 24348838, 2014). "PEComas usually show immunoreactivity for both melanocytic (HMB-45 and/or melan-A) and smooth muscle (actin and/or desmin) markers." (PMID 24410788, 2014). "Nearly all PEComas show immunoreactivity for both melanocytic (HMB45 and/or Melan-A) and smooth muscle (actin and/or desmin) markers." (PMID 22953133, 2012). "PEComas stain most consistently for HMB-45, melan-A, and microphthalmia transcription factor and may also stain for S100." (PMID 34716849, 2021).
PEComas (continued). "PEComas share overlapping histopathological features with epithelioid cells along a perivascular distribution and characteristic immunohistochemistry with coexpression of myoid and melanocytic markers (HMB-45 /or Melan-A)." (PMID 26754205, 2016). "PEComas often share overlapping histopathological features with epithelioid cells along a perivascular distribution and characteristic immunohistochemistry with coexpression of myoid and melanocytic markers (HMB-45 /or Melan-A)." (PMID 26754205, 2016). "In addition to these morphologic attributes, PEComas will also lack immunoreactivity for epithelial or renal tubular markers and S100 and will be positive for HMB45 and Melan A." (PMID 26246933, 2015). "Therefore, nearly all PEComas are immunoreactive for HMB-45 and/or Melan-A, and many are positive for smooth muscle actin, whereas desmin staining appears to be somewhat less common." (PMID 18053181, 2007). "Although PEComas and clear-cell sarcoma of soft tissue share some phenotypic features, including positive reactivity to the melanocytic marker HMB-45 and Melan-A, clear-cell sarcoma of soft tissue exhibits dense fibrous septae rather than the delicate vascular-rich stroma of the PEComas." (PMID 23587410, 2013). "PEComas typically express melanocytic markers such as HMB45 and melan-A and are negative for cytokeratins and EMA." (PMID 40002892, 2025). "Both benign and malignant PEComas share certain immunohistochemical features; therefore, common markers such as HMB-45 and Melan-A do not differentiate between benign and malignant forms." (PMID 40647483, 2025). "The three PNL2 negative PEComas were all positive for HMB45, and 2/3 these cases were also Melan-A positive." (PMID 38664269, 2024). "Lack of immunoreactivity for HMB45, melan-A, desmin, pan-CK, PAX8, and S100 excluded the possibility of perivascular epithelioid cell tumor, clear cell sarcoma, metastatic renal cell carcinoma, granular cell tumor, and paraganglioma." (PMID 35626258, 2022). "Even though a few angiolipomas and other PEComas arising in non-renal locations (that is, liver, lungs, and so on) have been reported to have patchy or negative reactivity for melanosome markers, recent reviews consider that 100 percent of renal EAMLs are positive for either HMB-45 or Melan-A." (PMID 23628229, 2013).